MMP3 (matrix metallopeptidase 3)
Diseases named in the same sentence as MMP3 in open-access papers (continued):
Sharing a sentence is not in itself a finding about the gene and the disease.
joint disease (7 papers, 2013 to 2025). "Regarding joint disease, this enzyme represents a marker of synovial inflammation and cartilage degradation, with elevated serum MMP-3 levels being closely related to the disease severity." (PMID 41020853, 2025). "The thesis of increased—stimulated by MMPs—degradation of PGs/GAGs in the course of JIA is confirmed by significantly higher concentrations of MMP-1 and MMP-3 in the blood of patients with active arthropathy, who qualified for ETA therapy." (PMID 36009392, 2022). "Previous research studies have reported that other protein biomarkers implicated in the pathophysiology of joint disease, such as vascular endothelial growth factor-A (VEGF-A) and matrix metalloproteinase 3 (MMP3), are also correlated with disease activity." (PMID 23585841, 2013). "The findings of authors showed a decrease in the level of MMP-2, MMP-3 and MMP-9 in saliva of children with diagnosed arthropathy." (PMID 33668781, 2021). "The study concerning the assessment of MMPs in body fluids, i.e., in blood and synovial fluid (SF), confirm that children with JIA have high MMP-3 levels in comparison to healthy children regardless of the type of arthropathy, age and duration of disease." (PMID 33668781, 2021). "ROMs: reactive oxygen metabolites, CRP: C-reactive protein; MMP-3: matrix metalloproteinase-3, DAS28: 28-joint disease activity score, CDAI: clinical disease activity index, ESR: erythrocyte sedimentation rate; SDAI: simplified disease activity index, HAQ: health assessment questionnaire." (PMID 34938634, 2021).
Sepsis (7 papers, 2014 to 2024). Sepsis is defined as life-threatening organ dysfunction caused by a dysregulated host response to infection. "Patients carrying the 6A allele in MMP3 rs3025058 had a higher probability of microbiologically-proven sepsis (HR 1.4." (PMID 35204780, 2022). "At present, therefore, we report the association of virus sepsis diagnosis with a functional genetic variant of MMP-3." (PMID 35204780, 2022). "GPs of MMPs and TIMP (namely MMP-1 rs1799750, MMP-3 rs3025058, MMP-8 rs11225395, MMP-9 rs2234681, and TIMP-1 rs4898) have been compared in 1058 patients with suspected sepsis to assess the association with susceptibility and etiology of sepsis." (PMID 35204780, 2022). "Other studies have identified other MMP variants as associated with sepsis susceptibility or prognosis: MMP-1, MMP-3, MMP-8, and TIMP-1 variants have already been investigated in sepsis outcome in a few hundred ICU patients with severe sepsis." (PMID 35204780, 2022). "Among the MMPs showing earlier increased plasma levels in sepsis were MMP-3, -8, and -10 as we observed while others like MMP-1 and -9 increased later." (PMID 24833564, 2014). "Among patients with sepsis, carriers of MMP1 rs1799750 G/G have an increased susceptibility for intracellular pathogen infections, while virus serology is more often positive in those with the MMP3 rs3025058 A/A genotype." (PMID 35204780, 2022). "Elevated levels of MMP-3 have also been observed in patients with sepsis." (PMID 33371324, 2020). "Furthermore, it was found that MMP-3 levels decreased gradually in line with the progression of sepsis." (PMID 33371324, 2020). "Along these lines, RvD2 in murine model of sepsis increases MMP-2 and MMP-3 in infectious exudates (and references within)." (PMID 39294573, 2024). "The association of the MMP-1 (-1607 1G/2G) SNP and sepsis might be due to linkage disequilibrium with the MMP-13 SNP because the MMP-13 and MMP-1 genes are both located in the same cluster of the chromosome 11q22-23 along with the MMP-3, MMP-7, MMP-8, MMP-10, MMP-12, and MMP-20 genes." (PMID 24833564, 2014). "Gelatinases (MMP-2 and -9) have been related to sepsis so far although less attention has been paid to collagenases (MMP-1, - 13) and stromelysins (MMP-3, -10)." (PMID 24833564, 2014). "Further, in an unpublished proteomics analysis for early sepsis (samples taken at median day 28 after HCT) neither DKK3 nor MMP3 were detected." (PMID 37526081, 2023). "Notably, Mmp3, a gene involved in the regulation of cardiac remodeling, can be directly regulated by JUN for both sepsis induction methods." (PMID 37510271, 2023). "We bring forward now the potential role of collagenases (MMP-13 and MMP-1) and perhaps stromelysins (MMP-3) in sepsis, an interesting finding because these MMPs are neither expressed in neutrophils nor released from neutrophils granules after endotoxin challenge as MMP-8 and MMP-9 do5." (PMID 24833564, 2014). "The present study reports the associations between MMP-8 rs11225395 G/G genotype and sepsis compared to patients without sepsis and, moreover, of the MMP-1 rs1799750 and MMP-3 rs3025058 genotypes with diagnosis of sepsis due to intracellular pathogens or virus, respectively." (PMID 35204780, 2022).
asthma (6 papers, 2016 to 2023). "Collectively, these results indicated that elevated epithelial SIRT6 promoted IL-17A release, which induced MMPs and cytokines (eg, Mmp3, Mmp12, and Cxcl1) scretion in severe asthma." (PMID 38135684, 2023). "MMP1, MMP3, MMP8, and MMP12 levels were associated with severe asthma and were correlated positively with sputum IL-5 levels but negatively with IL-13 levels." (PMID 26851968, 2016). "In stable mild-to-moderate asthma, MMP-2 in association with MMP-3 is released from bronchial fibroblasts and may have a negative effect on lung function and AHR." (PMID 31547356, 2019). "Since TNF alpha is localized to human mast cells, this creates the possibility for MMP-3 to act potentially as an activator of TNF alpha release, thereby enhancing the profibrotic course and influencing endothelial cell activation and the recruitment of infiltrating leucocytes in asthma." (PMID 33920429, 2021).
autoimmune disease (6 papers, 2012 to 2023). A disorder resulting from loss of function or tissue destruction of an organ or multiple organs, arising from humoral or cellular immune responses of the individual to their own tissue constituents. "A pathogenic role of MMP-3 dependent cleavage of agrin in neurological disorders has been suggested in addition to being associated with autoimmune diseases." (PMID 22984437, 2012). "Since GCs are observed in the lesions of autoimmune diseases and lymphomas, targeting the MMP3/TNFα-mediated migration of stromal cells in the B cell follicle may have great potential as a future therapeutic modality against aberrant GC-associated disorders." (PMID 34222497, 2021). "The ROC curve analysis revealed that MMP-3 displayed a good ability in distinguishing between those patients in the active phase of the disease from those without autoimmune disorders (AUC > 0.838)." (PMID 33664330, 2021). "Furthermore, chebulanin treatment decreased the expression of the autoimmune disease-related cytokines (TNF-α and IL-6) and enzymes (COX-2 and MMP-3), indicating that the therapeutic mechanism of chebulanin may involve inhibition of inflammatory signaling in the joints of CIA mice." (PMID 26402786, 2015). "The aim of the study was to evaluate the significance of MMP-3, CXCL-13 and C5a in different stages of AAV such as the active phase, short-term remission, long-term remission and comparing with patients without any autoimmune disorders." (PMID 33664330, 2021).
bladder cancer (6 papers, 2006 to 2025). "The content of MMP3 in bladder cancer tissue (0.2 μg/g protein) is significantly lower than in control bladder tissue (1.8 μg/g protein)." (PMID 41228251, 2025). "The enzymatic activity and the expression of MMP3 were higher in cell lines T24 and Biu87 from the malignant stage of bladder cancer than they were in bladder cancer cell lines 5637 and EJ from NMIBC." (PMID 39097778, 2024). "Low-grade urinary bladder cancer tissues were characterized by an increase of actual activity of MMP-3." (PMID 34441979, 2021). "The calculated specific activity of MMP-3 diminished with the increase in grade of urinary bladder cancer." (PMID 34441979, 2021). "Both low-grade and high-grade urinary bladder cancers contain a four-times lower level of MMP-3 than MMP-10." (PMID 34441979, 2021). "The actual and specific activities vary in both grades of urinary bladder cancer; however, the highest activity for MMP-3 and MMP-10 was found in low-grade tissues." (PMID 34441979, 2021). "That is why MMP-10 seems to be much more important and valuable in the course of urinary bladder cancer than MMP-3." (PMID 34441979, 2021). "ROC curves generated from ELISA were used for measuring the accuracy of both MMP9 and MMP3 at different stages of bladder cancer." (PMID 25135219, 2014). "Evaluating the urinary levels of MMP3 and MMP9 as diagnostic and prognostic biomarkers in different stages of schistosomal and non schistosomal bladder cancer was the aim of the present study." (PMID 25135219, 2014). "The highest specific activity of MMP-3 was found in low-grade urinary bladder cancer." (PMID 34441979, 2021). "However, further studies are required on large number of urine samples to confirm these results especially the role of MMP3 in the diagnosis of early stages of schistosomal and non schistosomal bladder cancer." (PMID 25135219, 2014). "MMP3 was elevated significantly in both schistosomal bladder cancer (0.169 ng/ml) and non schistosomal bladder cancer groups (0.269 ng/ml) compared to the control group (P < 0,001); with more significant increase in non schistosomal bladder cancer than schistosomal bladder cancer patients." (PMID 25135219, 2014). "MMP3 may be the recommended urinary metalloproteinases as early diagnostic biomarker in the early stages of both types of bladder cancer although both MMP9 and MMP3 can be used in the diagnosis of advanced stages." (PMID 25135219, 2014). "Therefore, it can be concluded that MMP-3 has no diagnostic importance, and its prognostic utility in bladder cancer is disputable." (PMID 34441979, 2021). "Several other MMPs are also considered as bladder cancer biomarkers: MMP1, MMP3, MMP7, MMP14, and MMP15." (PMID 41228251, 2025). "Urinary levels of both MMP-3 and MMP-9 were significantly elevated in all bladder cancer patients compared with controls." (PMID 25135219, 2014). "Generally, obtained results demonstrated a contrary participation of MMP-3 and MMP-10 in ECM remodeling what may be crucial in the pathogenesis of human urinary bladder carcinoma." (PMID 34441979, 2021). "The association between the urinary levels of MMP9 and risks of bladder cancer as well as stage and grade of disease was reported in different studies, but few studies are available for MMP3 levels in bladder cancer both schistosoma or non-schistosoma related." (PMID 25135219, 2014). "So in conclusion, measurements of urinary levels of MMP3 and MMP9 may aid in the diagnosis of both schistosomal and non schistosomal bladder cancer at different stages." (PMID 25135219, 2014). "Moreover, based on circulating plasma MMP-3 levels it was not possible to distinguish between bladder cancer patients and healthy controls, and they were not predictive for the bladder cancer-specific survival." (PMID 34441979, 2021).
bladder cancer (continued). "MMP-3 started to elevate in early stages of schistosomal bladder cancer ( 0.173 ng/ml) and non-schistosomal bladder cancer patients (0.308 ng/ml) compared to control (0.016 ng/ml) and remained elevated in advanced stages (0.166, 0.235 ng/ml) of both types of bladder cancer patients." (PMID 25135219, 2014). "Moreover, the current study is distinctive in reporting the role of urinary MMP3 in bladder cancer, whether of schistosomal or non-schistosomal origin." (PMID 25135219, 2014). "So the aim of the present study was to evaluate the urinary levels of MMP3 and MMP9 in different stages of schistosomal and non-schistosomal bladder cancer in Egyptian patients." (PMID 25135219, 2014). "This may explain the increase in urinary levels of MMP3 rather than MMP9 in the early stages of both schistosomal and non schistosomal bladder cancer patients." (PMID 25135219, 2014).
colorectal tumor (6 papers, 2017 to 2025). "A recent large scRNA-Seq analysis of colorectal tumours revealed a ‘myeloid-cell-attracting’ hub consisting of inflammatory monocytes, neutrophils and MMP3 + CAF hypothesised to be associated with tissue damage and microbial products." (PMID 39757146, 2025). "Elevated expressions of MMP-3, MMP-9, and MMP-13 in colorectal tumors in Min/OPN(+/+) mice were decreased by OPN deficiency." (PMID 28505114, 2017). "In conclusion, this study confirmed that APRIL/TNFSF13, BAFF, and MMP-3 are overexpressed in colorectal tumor tissues and the overexpression of APRIL/TNFSF13, BAFF, and MMP-3 indicates their potential relationship with unfavorable clinicopathological features and poor prognosis of CRC." (PMID 37511338, 2023). "MMP-3, MMP-9, MMP-13, MMP-2, and MMP-7 were upregulated in colorectal tumors in Min/OPN(+/+) compared to adjacent non-tumor parts." (PMID 28505114, 2017).
emphysema (6 papers, 2013 to 2021). "Recent studies have suggested that MMP3 polymorphisms are also important in the pathogenesis and severity of emphysema." (PMID 30563576, 2018). "MMP-3, and -10 associated with all emphysema sub-types other than mild CLE, while MMP-7 and -8 had associations with moderate and severe CLE and PSE." (PMID 27460105, 2016). "MMP-3 and -10 had associations with all of these sub-types, suggesting they play an important part in the tissue destruction seen in these sub-types of emphysema." (PMID 27460105, 2016). "We have previously reported MMP-3, -7 and -10 were associated with overall quantitative measures of emphysema while Chaudhuri found MMP-9 and -12 were associated with this measure." (PMID 27460105, 2016). "MMP-3 and -10 had significant associations with all forms of emphysema (apart from mild CLE) while MMP-7, -8 and -9 had associations with multiple sub-types." (PMID 27460105, 2016). "We have previously reported that overall emphysema had associations with MMP-3, -7 and -10 and CT markers of small airways disease had associations with MMP-3, -7, -8, -9, -10 and -12." (PMID 27460105, 2016). "MMP-3 and -10 had significant associations with all emphysema sub-types apart from mild CLE." (PMID 27460105, 2016). "Matrix metalloproteinases 1 and 9 are important in the stability of the extracellular matrix in various tissues including the lung; however the role of MMP3 in the pathogenesis of emphysema is less clear." (PMID 30563576, 2018). "Moreover, SIRT1 overexpression, by downregulation of MMP-1 and MMP-3, has beneficial effect on mice emphysema and human COPD." (PMID 33917352, 2021). "Furthermore, all emphysema sub-types, apart from mild CLE, had associations with multiple MMPs, particularly the stromelysins MMP-3 and MMP-10, implicating these proteases in the tissue destruction that occurs in these sub-types of emphysema." (PMID 27460105, 2016).
esophageal cancer (6 papers, 2020 to 2023). A primary or metastatic malignant neoplasm involving the esophagus. "In previous studies, it has been shown that the genes and proteins of FGFR-1 and MMP3 are highly expressed in esophageal squamous cell carcinoma, and may be associated with esophageal cancer invasion and metastasis." (PMID 35227278, 2022). "The research has indicated that increased MMP3 can extremely drive the metastasis of esophageal cancer cells." (PMID 36033831, 2022). "In this study, we found ERK phosphorylation, VEGFA and MMP3 were also inhibited after MAP4 knockdown, further confirmed that MAP4 played an important role in promoting esophageal cancer." (PMID 36991467, 2023).
head and neck squamous cell carcinoma (6 papers, 2010 to 2025). A squamous cell carcinoma that arises from any of the following anatomic sites: lip and oral cavity, nasal cavity, paranasal sinuses, pharynx, larynx, and salivary glands. "Head and neck squamous cell carcinoma (HNSCC) cells with FSP-1 knockdown exhibited reduced expression of matrix metalloproteinase 3 (MMP3), resulting in decreased invasiveness and metastasis in vivo." (PMID 39780187, 2025). "In head and neck squamous cell carcinoma high expression level of MMP3 was correlated with 5A/5A genotype and with the worst response to 5FU-cisplatin neoadjuvant chemotherapy." (PMID 24804215, 2014). "MMP-3 transcription is higher in head and neck squamous cell carcinoma (HNSCC) and several other types of malignancies including lung and breast carcinomas." (PMID 20630073, 2010).
heart failure (6 papers, 2017 to 2026). Inability of the heart to pump blood at an adequate rate to meet tissue metabolic requirements. "Accumulating evidence indicate that MMP proteins, including MMP3 (also known as stromelysin-1), are closely associated with MI and heart failure." (PMID 37188676, 2023). "Matrix metalloproteinase 3 (MMP3), in conjunction with other MMPs, plays a key role in myocardial remodeling by breaking down the extracellular matrix of the heart and the development of heart failure (HF)." (PMID 41751834, 2026). "Together, these data suggest that MMP-3 may contribute to ventricular remodeling in specific forms of heart failure, resulting in impaired electrical conductivity." (PMID 34442348, 2021). "Our study, to the best of our knowledge, is the first to examine potential associations with MMP-3 5A/6A polymorphisms and cardiac conduction in a cohort of patients without heart failure." (PMID 34442348, 2021).
metastatic cancer (6 papers, 2016 to 2024). A carcinoma which has spread from the original site of growth to another anatomic site. "While MMP9 activity performed opposite to MMP3 activity (increased in activity level from the healthy control to pancreatitis, metastatic cancer, and localized pancreatic cancer, respectively), the significant differences between groups tested was similar." (PMID 40292193, 2024). "Mean concentrations of MMP-3 were significantly higher in patients with metastatic prostate cancer as compared with those with non-metastatic cancer, patients with benign prostate hyperplasia, and healthy controls." (PMID 33371324, 2020). "Earlier studies have shown upregulation of MMP3 in mortalin-enriched metastatic cancer cells." (PMID 36172283, 2022).
systemic lupus erythematosus (6 papers, 2015 to 2024). An autoimmune multi-organ disease typically associated with vasculopathy and autoantibody production. "Elevated MMP3 is also associated with inflammatory arthritis, lupus, and mouse models of lung injury." (PMID 35439171, 2022).
tuberculosis (6 papers, 2009 to 2023). A chronic, recurrent infection caused by the bacterium Mycobacterium tuberculosis. "Monocyte-microglial network-dependent MMP-1 and MMP-3 gene expression and secretion are dependent upon p38 MAPK in tuberculosis." (PMID 23978194, 2013). "It has been shown that calcitriol upregulates MMP-3 expression in chondrocytes, but downregulates MMP levels in tuberculosis-infected leukocytes." (PMID 23144765, 2012). "Of note MMP-3, -8, -9 and TIMP-1 fell and TIMP-4 rose significantly over the course of 9 months anti-tuberculosis treatment." (PMID 19789647, 2009). "Tuberculosis (TB) of the central nervous system (CNS) is characterized by extensive tissue inflammation, driven by molecules that cleave extracellular matrix such as matrix metalloproteinase (MMP)-1 and MMP-3." (PMID 23978194, 2013). "MMP-1, MMP-3, MMP-7, and MMP-10 gene expression was analyzed by quantitative RT-PCR in M. tuberculosis stimulated PBMCs from 16 TB-IRIS participants treated with prednisone therapy compared with 12 patients who were placebo treated over 4 weeks of prednisone versus placebo treatment." (PMID 24136296, 2014). "Upon stimulation with M. tuberculosis for 6 h, several of the MMP transcripts including MMP-1, MMP-3, MMP-7, and MMP-10 (pcorr ≤ 0.05) increased in abundance in both TB-IRIS and non-IRIS patients when compared with those of unstimulated cultures." (PMID 24136296, 2014).